ENSG00000274625
Synonyms: LOC124905174
Gene: Small Cajal body-specific RNA gene on chromosome 22 (18,605,355 to 18,605,497, forward strand). Ensembl gene ENSG00000274625.
Gene Ontology:
Biological process: RNA processing
Cellular component: Cajal body; nucleolus